DDX6 (DEAD-box helicase 6)
Diseases named in the same sentence as DDX6 in open-access papers (continued):
Sharing a sentence is not in itself a finding about the gene and the disease.
lung adenocarcinoma (1 paper, 2024). A carcinoma that arises from the lung and is characterized by the presence of malignant glandular epithelial cells. "Taken together, our work indicates that Rab3B is upregulated in LKB1-deficient lung adenocarcinoma cells and drives lung adenocarcinoma progression through interaction with and stabilization of DDX6 protein." (PMID 38834947, 2024). "Specifically, depletion of DDX6 blocks the proliferation, colony formation, and migration of lung adenocarcinoma cells in vitro, as well as tumorigenesis in vivo." (PMID 38834947, 2024). "Ectopic expression of DDX6 significantly promoted the proliferation, colony formation, and migration of lung adenocarcinoma cells." (PMID 38834947, 2024). "We also reveal an interaction between Rab3B and DDX6, which contribute to the aggressive phenotype in lung adenocarcinoma cells both in vitro and in vivo." (PMID 38834947, 2024). "Most importantly, ectopic expression of DDX6 can partially rescue the proliferation, colony formation, and migration potential in Rab3B-depleted lung adenocarcinoma cells." (PMID 38834947, 2024). "In this study, we show that there is an interaction between Rab3B and DDX6 in lung adenocarcinoma cells." (PMID 38834947, 2024). "Additionally, DDX6 overexpression partially rescued the aggressive phenotype of Rab3B-depleted lung adenocarcinoma cells." (PMID 38834947, 2024). "Rab3B-meidated aggressive phenotype in lung adenocarcinoma cells is impaired when DDX6 is silenced." (PMID 38834947, 2024). "DDX6 knockdown phenocopied the effects of Rab3B depletion on lung adenocarcinoma cells." (PMID 38834947, 2024). "Given the interaction between Rab3B and DDX6, we speculated that DDX6 might be involved in lung adenocarcinoma progression." (PMID 38834947, 2024). "In contrast, overexpression of DDX6 enhances the aggressiveness of lung adenocarcinoma cells." (PMID 38834947, 2024). "Interestingly, we demonstrate that DDX6-depleted lung adenocarcinoma cells recapitulate the phenotype of Rab3B-depleted counterparts." (PMID 38834947, 2024). "Rab3B interacts with and stabilizes DDX6 protein to accelerate lung adenocarcinoma progression." (PMID 38834947, 2024). "However, the mechanism by which DDX6 promotes lung adenocarcinoma progression needs to be clarified in future work." (PMID 38834947, 2024).
metastatic tumor (1 paper, 2017). "Overall, these data suggest that DDX6 knockout not only inhibits primary and metastatic tumor growth but also decreases systemic dissemination, consistent with inhibition of EMT." (PMID 29262563, 2017).
myeloid malignancies (1 paper, 2015). "DDX6 was identified as the second gene within this region, after MLL, to be specifically up regulated in myeloid malignancies even in the absence of 11q23.3 amplification." (PMID 26610392, 2015).
myocardial ischemia (1 paper, 2024). A disorder of cardiac function caused by insufficient blood flow to the muscle tissue of the heart. "Interestingly, contrary to previous myocardial ischemia-reperfusion research, VIRMA (also known as KIAA1429) also participates in the binding of DGCR8 to pri-miR143-3p, in which the target gene is DEAD-box helicase 6 (DDX6)." (PMID 38988324, 2024).
PURA Syndrome (1 paper, 2023). "As PURA Syndrome is described to result from a haploinsufficiency and thereby lowered cellular PURA levels, our findings on PURA-dependent, LSM14A/DDX6-mediated P-body formation could potentially relate to a molecular dysfunction in patients." (PMID 36651277, 2023).
T cell lymphomas (1 paper, 2019).
tauopathies (1 paper, 2021). "DDX6 was found to increase the activity of miR-21 and miR-124 by interacting with Tau protein in tauopathies." (PMID 34374627, 2021).
teratocarcinoma (1 paper, 2021). A germ cell tumor characterized by the presence of an embryonal carcinoma component and a teratoma component. "Former studies revealed that ELAVL2 promotes translation of targeting mRNAs containing AU‐rich elements by accelerating the formation of translation initiation complexes, like GLUT1 in adipocytes, DDX6 in oocytes, and neurofilament M in human teratocarcinoma cells." (PMID 34296486, 2021).
cancer (24 papers, 2009 to 2025). A tumor composed of atypical neoplastic, often pleomorphic cells that invade other tissues. "Among the numerous cancer-associated studies, reports revealed that DDX6 can affect cancer progression by controlling miRNA biogenesis or activity." (PMID 38689093, 2024). "DDX6 expression is associated with the IRES-dependent c-MYC translation to regulate cancer cell growth and differentiation." (PMID 34887764, 2021). "Based on this evidence, DDX6 may be associated with miRNA-regulatory roles in cancer progression." (PMID 38689093, 2024). "The genes BLK, CDC247, CSK, IRF5, STAT1, STAT4, and TNIP1 are associated with AIDs, and CDC37, DDX6, HSPA6, MAPT, PPIB, STAT1, and STAT4 are associated with cancers." (PMID 40429780, 2025). "The genes BLK, FAM167A, STAT1, STAT4, TNPO3, and TNIP1 are associated with AIDs, and CDC37, DDX6, MAPT, STAT1, STAT4, and UBE3A are associated with cancers." (PMID 40429780, 2025). "Specifically, Rab3B interacts with and potentiates the stability of DDX6, which endows cancer cells with more aggressiveness." (PMID 38834947, 2024). "DDX6 participates in various RNA metabolisms and has a wide expression pattern (e.g., in pluripotent cells, adult tissue stem/progenitor cells, cancer, and RNA-virus infected cells)." (PMID 36197846, 2022). "In our previous studies, we detected the overexpression of DDX6 in most of the tumor samples and cell lines examined, and found that DDX6 positively regulates c-Myc expression at the translational step in various cancers." (PMID 30959742, 2019). "Significantly increased expression of DDX6 was also found in other cancer cells." (PMID 36834609, 2023). "In addition, cancer susceptibility 2 (CASC2) and cancer susceptibility 19 (CASC19) have been demonstrated to exhibit proinflammatory and proapoptotic effects by regulating IL-17 and the miR-152-3p/DDX6 axis, respectively." (PMID 37189327, 2023). "Our analyses of the TCGA data show that DDX6 is downregulated in multiple cancers." (PMID 36761420, 2022). "DDX6 is an oncogenic RNA helicase frequently overexpressed in multiple cancers, including CRC." (PMID 34887764, 2021). "As the persistence of pre-existing transcripts blocks reprogramming via the RO60/ DDX6 axis, the molecular components in the axis could be a target for modulating cancer metastasis." (PMID 30273347, 2018). "This revealed that few of the helicases are always lost across the cancers examined, such as DDX3X and DDX6." (PMID 36761420, 2022). "Among these genes, PICALM (targeted by EP300), DDX6 (targeted by YY1) and LYL1 (targeted by LMO2) are reported on the COSMIC cancer gene list." (PMID 32850701, 2020). "DDX6 was overexpressed in hepatitis C virus (HCV)-HCC tissues and promoted tumor growth via controlling the replication of HCV in cancer cells." (PMID 33614480, 2020). "Interestingly, expression of DDX6 ubiquitylation mutant promotes P-body disassembly and accelerates GBM growth, thus indicating that cAMP-induced DDX6 ubiquitylation represents a negative constraint on protein translation and cancer cell growth." (PMID 40148504, 2025). "The remaining genes are a part of several pathways involved in cancer etiology such as: Negative regulation of stress activated MAPK cascade (PBK and PINK1), intracellular signal transduction and regulation of autophagosome assembly (LRRK2 and PINK1) and RNA degradation (PABC3 and DDX6)." (PMID 29879995, 2018). "Strikingly, knockout of the P-body-nucleation-determining genes DDX6 and LSM14A inhibited proliferation in multiple cancer cell lines (negative Chronos score)." (PMID 39046443, 2024).
tumor (12 papers, 2016 to 2025). "Conversely, genes over-expressed in MIF low/Ddx6 high samples were enriched (p = 5.09E–05) for genes down-regulated in the same study, thus supporting the association of high human MIF and low mouse Ddx6 expression with tumor hypoxia." (PMID 26980748, 2016). "Downregulation of DDX6 reduced the viability, caused cell cycle arrest in S phase, induced apoptosis, and decreased the Warburg effect in CRC cells and suppressed tumor growth in nude mice." (PMID 38023215, 2023). "Our data suggest a potential stromal role for DDX6 in the hypoxia response as an alternative to its previously established tumor-specific activity, and a potential link with MIF activity in the tumor." (PMID 26980748, 2016). "Increased MIF expression and reduced DDX6 expression are both known drivers of angiogenesis and strongly associated with VEGF activity, as such they have been implicated in tumor response to hypoxia." (PMID 26980748, 2016). "In fact, expression of DDX6 mutant deregulates P-body formation and, probably, translation of selected RNA transcripts that may, thus, contribute to tumor cell growth." (PMID 40148504, 2025). "DDX6 is located to the processing bodies (P-bodies) in somatic, stem and tumor cells." (PMID 38023215, 2023). "By reexpression of PNRC1 or knockdown of P-body core genes (DDX6, DCP1A, and LSM14A), we determined that disruption of P-bodies attenuates cell proliferation, cell migration, and tumor growth induced by overexpression of YAP5SA in CRC." (PMID 39046443, 2024). "Except for three RBPs (SNRNP48, DDX6, and ZC3HAV1) out of the 63, the high-expression tumor group had worse clinical outcome for RBPs that were upregulated in IR-1." (PMID 33311498, 2020). "In conclusion, syn-miR-143 exhibited its anti-tumor effect on HER2-positive GC by impairing the KRAS networks systematically, including DDX6 RNA helicase." (PMID 30959742, 2019). "First, we used Western blotting to investigate the expression levels of DDX6, HER2, and FGFR2 in 20 GC clinical tumor samples." (PMID 29987267, 2018). "Blockage of P-body formation by disruption of the gene for DDX6, a protein essential for P-body assembly, blocks EMT and prevents tumor cell metastasis in vivo." (PMID 29262563, 2017).
infection (11 papers, 2011 to 2025). The state of being infected such as from the introduction of a foreign agent such as serum, vaccine, antigenic substance or organism. "Higher level expression of VP35 seen in advanced stages of infection also caused loss of EDC4 puncta associated with DDX6, a marker of P-bodies, suggesting disruption of normal P-body organization." (PMID 41006235, 2025). "Besides signaling responses, this study uncovers the role of PBs in HSV-1 infection and suggests that infection progression depends on degradation or aggregation of DDX6 and loss of PBs." (PMID 37500668, 2023). "We then performed a time-course experiment wherein OC43-infected HUVECs were fixed at various times post infection and immunostained for the viral N protein and the PB-resident protein DDX6." (PMID 35998203, 2022). "In lieu of this, we performed additional OC43 and 229E infections and co-stained infected cells using antibodies for Hedls and DDX6." (PMID 35998203, 2022). "Infected cells were identified by immunostaining for N protein 24 hours post infection and PBs were stained for DDX6 and Hedls." (PMID 35998203, 2022). "DDX6 knockdown decreased the expression of interferon-stimulated factors in response to EV71 early infection." (PMID 34485180, 2021). "Coimmunoprecipitation assays detected a basal level of complexes harboring RIG-I and DDX6 that increased after infection." (PMID 29949917, 2018). "After infection, a significant amount of DDX6, normally concentrated in P bodies and stress granules, re-localizes to the pericentriolar site where viral RNAs and Gag capsid proteins are concentrated and capsids are assembled." (PMID 22022269, 2011). "MCU analysis implied that DDX6 has an antiviral role in HSV-1 infection, and we observed that the mean intensity of DDX6 decreased in HSV-1-infected HeLa cells at the late stages of infection." (PMID 37500668, 2023). "Additionally, we show that the levels of crucial PB proteins (DDX6, AGO2 and TNRC6A) remain unchanged during infection." (PMID 21390246, 2011). "Interestingly, in the absence of infection, we observed endogenous proteolysis of proteins known to be cleaved by enteroviruses, including DDX6, HNRPM, EIF5B, G3BP1, and eIF4G1/2." (PMID 38918600, 2024). "Similarly, three helicase members, DDX6, DDX17, and DDX23 were shown to restrict the replication of RVFV in Drosophila, in which DDX17 binds the essential stem loop in bunya viral RNA to combat infection." (PMID 31620127, 2019).
neurodegenerative disease (1 paper, 2024). A disorder of the central nervous system characterized by gradual and progressive loss of neural tissue and neurologic function. "Thus, sequestration of DDX6 by PQE Atx2 aggregates could be considered as an alternative pathomechanism for SCA2 and other neurodegenerative diseases." (PMID 38810698, 2024).
DDX6 also shares sentences with these, for which no sentence is quoted: triple-negative breast carcinoma (2 papers); ZIKV infection (2); autosomal dominant intellectual disability (1); blood cancer (1); Cognitive Deficits (1); colorectal cancer (1); depression (1); dermatitis (1); developmental delays (1); eczema (1); lung carcinoma (1); lymphoma (1); malaria (1); malignant glioma (1); myeloid leukemia (1); Myocardial fibrosis (1); myocardial infarction (1); neuroblastoma (1); neurodevelopmental disorder (1); Neurological disorders (1); schizophrenia (1); testicular embryonal carcinoma (1).